NOG (noggin)
Description:
Inhibitor of bone morphogenetic proteins (BMP) signaling which is required for growth and patterning of the neural tube and somite. Essential for cartilage morphogenesis and joint formation. Inhibits chondrocyte differentiation through its interaction with GDF5 and, probably, GDF6.
Synonyms: SYM1; SYNS1; SYNS1A
Tractability: Antibody: its Gene Ontology location is reachable by antibodies, with high confidence; UniProt places it where antibodies can reach, with medium confidence; UniProt predicts a signal peptide or a membrane-spanning region.
Gene: Protein-coding gene on chromosome 17 (56,593,699 to 56,595,611, forward strand). Ensembl gene ENSG00000183691.
Subcellular location: Secreted
Pathways (Reactome):
Developmental Biology: Formation of paraxial mesoderm
Signal Transduction: Signaling by BMP
Gene Ontology:
Molecular function: growth factor binding; protein binding; protein homodimerization activity; receptor ligand inhibitor activity
Biological process: cell differentiation in hindbrain; dorsal/ventral pattern formation; embryonic digit morphogenesis; embryonic skeletal joint morphogenesis; embryonic skeletal system development; limb development; mesoderm development; middle ear morphogenesis; negative regulation of BMP signaling pathway; negative regulation of canonical Wnt signaling pathway; negative regulation of cell migration; negative regulation of osteoblast differentiation; negative regulation of SMAD protein signal transduction; neural plate anterior/posterior regionalization; nodal signaling pathway; regulation of fibroblast growth factor receptor signaling pathway; somatic stem cell population maintenance; atrial cardiac muscle tissue morphogenesis; endocardial cushion formation; epithelial to mesenchymal transition; heart trabecula morphogenesis; membranous septum morphogenesis; negative regulation of astrocyte differentiation; negative regulation of cardiac epithelial to mesenchymal transition; negative regulation of cardiac muscle cell proliferation; and 28 more
Cellular component: extracellular region; presynapse
Genetic constraint (gnomAD): Loss-of-function variants: 2 observed, 17.15 expected, observed/expected ratio (o/e) 0.12, 90% interval 0.047 to 0.37. The upper end of that interval is the gene's LOEUF score, 0.37, which puts it in group 1 of 6, group 1 being the genes least tolerant of losing a copy. Missense variants: 266 observed, 336.67 expected, observed/expected ratio (o/e) 0.79, 90% interval 0.71 to 0.88. Synonymous variants: 166 observed, 156.97 expected, observed/expected ratio (o/e) 1.06, 90% interval 0.93 to 1.2.
Gene-disease validity (ClinGen):
ClinGen rates the evidence that NOG causes each of these diseases.
NOG-related symphalangism spectrum disorder (autosomal dominant): Definitive. An autosomal dominant condition caused by pathogenic variants of the NOG gene, encoding the noggin protein.
Homologues: Orthologues: macaque NOG (100% identical), chimpanzee NOG (99% identical), mouse Nog (99% identical), pig NOG (99% identical), rat Nog (99% identical), rabbit NOG (98% identical), dog NOG (91% identical), guinea pig NOG (81% identical), tropical clawed frog nog (76% identical), zebrafish nog3 (59% identical), zebrafish nog1 (56% identical).
Diseases named in the same sentence as NOG in open-access papers:
NOG is named in the same sentence as 132 diseases in open-access papers, as found by Europe PMC text mining. Sharing a sentence is not in itself a finding about the gene and the disease. The quoted sentences say what the papers report.
Osteopenia (9 papers, 2008 to 2024). Osteopenia is a term to define bone density that is not normal but also not as low as osteoporosis. "Overexpression of murine noggin has been associated with impaired function of osteoblasts, resulting in osteopenia, fractures and decreased bone formation rate." (PMID 31323019, 2019). "The appropriate Noggin levels in vivo may also matter, as Noggin inactivation reportedly caused osteopenia in mice." (PMID 38509118, 2024). "For example, a transgenic mouse overexpressing noggin exhibited decreased trabecular bone volume and osteopenia." (PMID 24959229, 2014). "Animal studies have shown that transgenic mice overexpressing noggin suffered from long bone fractures and osteopenia, whereas the knockout noggin mouse was lethal with severe skeletal defects, such as multiple joint fusions." (PMID 21310029, 2011). "Transgenic mice over-expressing noggin in the bone microenvironment have decreased trabecular bone volume and impaired osteoblastic function, leading to osteopenia and fractures." (PMID 18533030, 2008). "Mice with osteoblast-specific overexpression of BMP-4 have been shown to develop severe osteopenia due to increased numbers of osteoclasts, whereas mice overexpressing Noggin, a BMP-4 antagonist, have shown increased bone volume due to reduced numbers of osteoclasts." (PMID 38047271, 2023). "Osteoblast-targeted over-expression of noggin results in osteopenia as the result of impaired osteoblast recruitment, indicating that the extracellular modulation of the BMP concentration is also essential in adult life for the control of bone formation during bone remodeling." (PMID 21249149, 2011).
prostate carcinoma (9 papers, 2011 to 2021). A carcinoma that arises from epithelial cells of the prostate gland. "Although the function of BMP signaling in tumorigenesis and tumor progression remains controversial, the overexpression of Noggin leads to decreased tumor size and reduced bone metastatic tumor growth in prostate cancer and lung cancer models." (PMID 34001012, 2021). "With the addition of DKK-1 and Noggin (antagonist of BMPs) to the conditioned medium, the activity of prostate cancer-induced osteoblast differentiation was diminished." (PMID 31137764, 2019). "Treatment of prostate cancer’s osteolytic bone metastasis with Noggin has also shown to be a potentially successful strategy." (PMID 23840733, 2013). "In addition, the BMP-antagonist noggin appears to facilitate decreased bone formation in an animal model of prostate cancer bone metastasis and in a number of osteolytic cell lines in vitro with prostate-derived cancer cell lines expressing higher levels of noggin than breast cancer derived cells." (PMID 24069136, 2013). "BMP2 has been specifically associated with the migratory and invasive capacity of prostate and liver cancer cells in vitro, while the BMP antagonist, Noggin, inhibits the migration of BMP2-stimulated prostate cancer cells." (PMID 32708289, 2020). "Previously, we reported that prostate cancer cells secrete the BMP antagonist, noggin, and, thereby, bone formation is inhibited." (PMID 29988965, 2018). "Depletion of ZEB1 in the prostate cancer cell line DU145, which is known to form osteolytic bone metastases, again decreased the expression of NOG mRNA and protein, as well as FST." (PMID 25973542, 2015). "Additionally, osteolytic prostate cancer cells secrete the bone morphogenetic protein (BMP) antagonist, noggin, which blocks bone formation, contributing to the progression of the osteolytic lesion." (PMID 29988965, 2018).
breast carcinoma (8 papers, 2013 to 2025). "High expression levels of Noggin are associated with bone metastases in both cell line/murine models and clinical samples of breast cancer bone metastases." (PMID 28733469, 2017). "Noggin regulates the ability of metastatic breast cancer cells to colonize bone tissue by promoting osteoclast differentiation and other mechanisms." (PMID 40277903, 2025). "High expression of Noggin has been implication in osteolytic bone metastases of breast cancer, reflecting its antagonism of BMP signalling." (PMID 37333824, 2023). "The BMP antagonist Noggin significantly inhibits FOXF2-driven osteolytic bone metastasis of breast cancer cells." (PMID 31222004, 2019). "Therefore the tumour-induced osteoblast regulation appears to rely on secreted factors from the cancer cells, further supporting the important role of paracrine molecules such as DKK-1 and Noggin in modulation of osteoblast function by breast cancer cells." (PMID 24069136, 2013). "However, the exact role of Noggin in breast cancer is yet to be fully evaluated." (PMID 37333824, 2023). "Others have highlighted that Noggin could inhibit BMP4-induced EMT and Notch gene expression in MCF-10A breast cancer cells." (PMID 40277903, 2025). "Moreover, amplification and/or upregulation of BMPs as well as BMP-antagonists, including NOG, GREM1, GREM2, and CHRD have been reported in breast cancer." (PMID 31694641, 2019). "In addition, BMP agonists that are engineered to prevent interactions with Grem1, as has been performed for Noggin, or BMP-mimetic small-molecule drugs, could be beneficial in the treatment of breast cancer patients with high Grem1 expression." (PMID 31533776, 2019).
Stroke (7 papers, 2012 to 2022). Sudden impairment of blood flow to a part of the brain due to occlusion or rupture of an artery to the brain. "Transplantation of nerve growth factor (NGF) and Noggin overexpressed BMSCs significantly facilitated the survival of BMSCs in stroke." (PMID 35695696, 2022). "A predictive model with 89.6% accuracy was identified using 6 network-central and differentially expressed genes (ID3, MBTPS1, NOG, SFXN2, BMX, SLC22A1), characterized by large differences in association network connectivity between stroke and control samples." (PMID 31391037, 2019). "Consistent with our results and in support of a role of Smad1 in mediating canonical BMP signaling in stroke, Noggin, an endogenous BMP antagonist, has been shown to confer protection against ischemic brain injury." (PMID 26317208, 2015). "The 9cRA –mediated reduction in cerebral infarction in stroke rats was significantly antagonized by the BMP antagonist noggin, suggesting that 9cRA induces protection through BMP7." (PMID 23040108, 2012). "The antagonistic action of noggin against BMP7 has been documented in stroke brain." (PMID 28674431, 2017). "Interestingly, the reduction of TUNEL labeling by 9cRA in stroke brain was antagonized by the BMP antagonist noggin." (PMID 23040108, 2012). "Expression values from the genes ID3, MBTPS1, NOG, SFXN2, BMX, and SLC22A1 can jointly distinguish stroke from non-stroke samples with a high level of accuracy: 89.6% of samples are correctly classified in cross-validation sampling." (PMID 31391037, 2019). "The mRNAs of ID3, MBTPS1, NOG, and SFXN2 have lower concentrations (are down-regulated) in the stroke samples (log FC = − 0.915, − 0.356, − 0.752, − 0.301, respectively) while BMX and SLC22A11 are up-regulated (log FC = 0.456, 0.365) in the stroke patients." (PMID 31391037, 2019).
craniosynostosis (5 papers, 2014 to 2023). Craniosynostosis is defined as the premature fusion of one or more cranial sutures leading to secondary distortion of skull shape resulting in skull deformities with a variable presentation. "As expected, we revealed that control release of Noggin via PLGA microspheres significantly blocked the fusion in atRA-induced craniosynostosis in mice." (PMID 30392121, 2019). "The proposed control release of Noggin via PLGA microspheres might be useful therapeutic strategy for rescuing atRA-induced craniosynostosis." (PMID 30392121, 2019). "In turn, Noggin overexpression in skulls of healthy mice prevents natural suture fusion; and application of ectopic recombinant Noggin rescues rats overexpressing FGFR2 from the craniosynostosis phenotype, as well as prevents the recurrence of suture closure after they need to be surgically opened." (PMID 30340367, 2018). "In addition, recombinant Noggin has been reported to act as an inhibitor of craniosynostosis in rat calvarial coronal sutures with transplantation of human AS osteoblasts." (PMID 25003957, 2014). "Lastly, in order to determine whether aberrant regulation of genes known to be involved in the aetiology of craniosynostosis underpinned any of the defects we observed, we examined the expression of Noggin, FGFR1/pFGFR1, FGFR2, Runx2 and Twist1 by immunohistochemistry." (PMID 27756203, 2016).
melanoma (5 papers, 2010 to 2023). A malignant, usually aggressive tumor composed of atypical, neoplastic melanocytes. "Our current findings corroborate our previous results showing that spontaneous neural crest migration and malignant invasion of melanoma cells were abrogated by pre-treatment of the melanoma cell aggregates with noggin before transplantation into the chick embryo." (PMID 29716947, 2018). "In melanoma cells, noggin, lefty and the receptor blocker SB431542 reversed the migratory mesenchymal morphological phenotype back to the aggregate epithelial morphological phenotype and ablated the capability of invasive behavior in physiological skin reconstructs." (PMID 29716947, 2018). "However it appears that late-stage melanomas become resistant to the anti-growth and pro-apoptotic effects of BMPs by upregulation of Noggin, a BMP inhibitor." (PMID 24281103, 2010). "In aggressive melanoma cells, BMP antagonist Noggin confers the cells with a resistance to BMP749 and suppresses an EMT‐like transition of cells." (PMID 37688374, 2023). "Blocking either BMP or nodal signaling by antagonists (noggin, lefty), or the Alk4/5/7-receptor inhibitor SB431542, decreases EMT and invasion of melanoma cells in human epidermal skin reconstructs." (PMID 29716947, 2018). "To analyse a potential regulation of CTGF gene expression by BMPs, we incubated Mel Im melanoma cells with recombinant BMP4, BMP7 or the BMP inhibitors noggin and chordin, respectively." (PMID 21673687, 2011). "We previously demonstrated that the BMP-antagonist noggin blocked the EMT phenotype of melanoma cells in the neural crest and malignant invasion of melanoma cells in the chick embryo; vice-versa, malignant invasion was induced in human melanocytes in vivo by pre-treatment with BMP-2." (PMID 29454361, 2018).
Obesity (5 papers, 2016 to 2024). Accumulation of substantial excess body fat. "The association of obesity with increased Noggin levels in mesenchymal stem cells was confirmed in a preclinical, immunocompetent mouse model of spontaneous obesity and in human patients with elevated body mass index." (PMID 27746742, 2016). "Noggin was also reduced in diet-induced obesity in inbred mice." (PMID 38184275, 2024). "Genetic ablation of noggin in mouse preadipocyte and adipocyte reinforces the BMP4 signaling, resulting in uncontrolled adipogenesis as well as obesity." (PMID 36831329, 2023). "Imbalance in commitment programming indeed leads to uncontrolled AT expansion as a root of hypertrophic obesity, providing that BMP4 signaling is negatively regulated by the direct binding between BMP4 and their physiological inhibitors, such as noggin and gremlin." (PMID 36831329, 2023). "Matrix Gla protein (MGP), Noggin, Sclerostin (SOST), and Gremlin have been identified as several extracellular, intracellular and transcriptional BMP inhibitors that are upregulated in obesity and act as negative regulators of BMP signaling pathways, ultimately downregulating osteoblastogenesis." (PMID 27746742, 2016).
Arthritis (4 papers, 2015 to 2023). Inflammation of a joint. "This could cause less Noggin production by T cells in arthritis, which could lead to the unresponsiveness of rat PBMCs to TNF-α." (PMID 34830044, 2021). "Although we detected Nog expression in the mouse lung, increased systemic Noggin levels likely contribute to these effects as suggested earlier in arthritis models in this specific transgenic mouse strain." (PMID 25849157, 2015). "In a study on rheumatoid arthritis, the researchers showed in the methylated bovine serum albumin (mBSA)-induced arthritis mouse model that Noggin haploinsufficient (Noggin+/LacZ) mice had an increased number of CD4+ lymphocytes in their synovial fluid compared to wild type mice." (PMID 32486027, 2020). "In the murine model of arthritis, BMP inhibition by the systemic gene transfer of noggin—a BMP antagonist, which exerted preventive as well as therapeutic effects, depending on the time of administration (before or after the first symptoms of arthritis)." (PMID 37750896, 2023).
colon cancer (4 papers, 2013 to 2023). "To investigate the effect of VP on human colon cancers, we successfully modeled organoids from patients with colon cancer in a medium supplemented with the growth factors noggin, epidermal growth factor (EGF), human fibroblast growth factor 10 (FGF-10), HEPES, GlutaMAX, Y-27632, and A83-01." (PMID 34055773, 2021). "In the GCSC database, the methylation levels of FGF8, NOG, TCF15, TWIST1, TBX5, SIX2, and TIAM1 are higher in colon cancer." (PMID 34526059, 2021). "However, colon cancer cells also grew as flat, disc-like colonies when cultured with EGF plus Wnt, R-Spondin1 and Noggin." (PMID 23638973, 2013). "Our results show that established colon cancer cell lines can be cultured in 3-D matrigel, and like their original source, human CRC, do not require the presence of EGF, R-Spondin1, Wnt3a, or Noggin for proliferation and long term expansion." (PMID 23638973, 2013).
cyclopia (4 papers, 2015 to 2023). "The prechordal plate also expresses NOGGIN, and mice that are Chrd−/−; Nog+/− develop holoprosencephaly, indicative of midline patterning defects." (PMID 27184910, 2016). "Defective expression of physiological BMP antagonists such as Chordin and Noggin disrupted the development of the rostral neural ectoderm and downstream malformations in the forebrain on a spectrum including cyclopia, holoprosencephaly, and truncated rostral brain." (PMID 33562570, 2021). "In mice, a compound knock-out of two BMP antagonists, chordin and noggin, resulted in severe forebrain defects presenting cases of HPE with cyclopia but also more severe cases with aprosencephaly." (PMID 37175759, 2023).
gastric cancer (4 papers, 2018 to 2023). A primary or metastatic malignant neoplasm involving the stomach. "For example, in patients with gastric cancer, high Noggin expression is associated with a poor prognosis, and Noggin promotes the proliferation of gastric cancer cells by upregulating EGFR signaling." (PMID 38012621, 2023). "For patients with gastric cancer, high expression of noggin is significantly associated with reduced patient survival time, and noggin was described to inhibit BMP signalling in some contexts." (PMID 34841646, 2022). "Our recent study of Noggin in gastric cancer also revealed another dark side in cancers, as it facilitated proliferation of gastric cancer cells, by an upregulation of EGFR and its downstream signalling and also promoted EMT." (PMID 37333824, 2023). "The result suggests a limited role of Chordin, Follistatin, and Noggin in regulation of BMP signaling in gastric cancer." (PMID 29720137, 2018). "Noggin, a modulator of BMP signalling, was reported to correlate with reduced survival of patients with gastric cancer, and our data reproduce this observation now for patients with CRC." (PMID 34841646, 2022). "Noggin, a modulator of BMP signalling belonging to the group of BMP antagonists, was reported to correlate with reduced survival of patients with gastric cancer." (PMID 34841646, 2022).
adenoma (3 papers, 2022 to 2025). A neoplasm arising from the epithelium. "While large intestinal organoids require WENR for growth in vitro, adenoma organoids require only addition of EGF and Noggin (EN) to basic media for their growth in culture." (PMID 35260534, 2022). "We obtained crypts from the intestines of these mice (including adenomas) and derived intestinal organoids in the absence of R-Spondin (EN medium, EGF + Noggin)." (PMID 35314684, 2022).